PSG11 (pregnancy specific beta-1-glycoprotein 11)
Synonyms: PSBG-11; PSBG-13; PSG13; PSG14; MGC22484
Tractability: Antibody: UniProt places it where antibodies can reach, with high confidence; UniProt predicts a signal peptide or a membrane-spanning region; its Gene Ontology location is reachable by antibodies, with medium confidence.
Gene: Protein-coding gene on chromosome 19 (43,007,656 to 43,026,474, reverse strand). Ensembl gene ENSG00000243130.
Subcellular location: Secreted
Subcellular location (Human Protein Atlas): Vesicles; Predicted to be secreted
Pathways (Reactome):
Hemostasis: Cell surface interactions at the vascular wall
Gene Ontology:
Biological process: female pregnancy; heterophilic cell-cell adhesion; homophilic cell-cell adhesion
Cellular component: plasma membrane; extracellular region
Genetic constraint (gnomAD): Loss-of-function variants: 42 observed, 34.42 expected, observed/expected ratio (o/e) 1.22, 90% interval 0.95 to 1.58. The synonymous counts are far from expectation, so gnomAD's model fits this gene poorly and the ratio says little. Missense variants: 558 observed, 402.05 expected, observed/expected ratio (o/e) 1.39, 90% interval 1.29 to 1.49. Synonymous variants: 206 observed, 153.85 expected, observed/expected ratio (o/e) 1.34, 90% interval 1.19 to 1.5.
Homologues: Paralogues in human: PSG2 (90% identical), PSG3 (84% identical), PSG7 (84% identical), PSG8 (83% identical), PSG6 (83% identical), PSG1 (82% identical), PSG4 (81% identical), PSG9 (79% identical), PSG5 (59% identical), CEACAM1 (46% identical), CEACAM5 (43% identical), CEACAM8 (41% identical), and 12 more.
Diseases named in the same sentence as PSG11 in open-access papers:
PSG11 is named in the same sentence as 5 diseases in open-access papers, as found by Europe PMC text mining. Sharing a sentence is not in itself a finding about the gene and the disease. The quoted sentences say what the papers report.
preeclampsia (5 papers, 2012 to 2021). Preeclampsia is a hypertensive disorder of pregnancy that is characterized by new-onset hypertension with proteinuria presenting after 20 weeks of gestation, and depending on mild or severe forms may initially present with severe headache, visual disturbances, and hyperreflexia. "PSG11 gene copy-number loss and increased PSG9 levels are associated with a higher risk for preeclampsia, a serious pregnancy complication characterized by high blood pressure and proteinuria, also indicate different roles of PSGs in the establishment and maintenance of successful pregnancies." (PMID 33602137, 2021). "In support of our speculation, a recent report indicated that there could be a nominal relationship between PSG11 gene copy variation and the occurrence of preeclampsia." (PMID 23613906, 2013).
ovarian carcinoma (1 paper, 2014). A malignant neoplasm originating from the surface ovarian epithelium. "In addition, two genes related to glycoprotein synthesis, PSG11 and GALNT10, were found highly predictive for the overall survival time of ovarian cancer patients." (PMID 25551281, 2014).
tumor (3 papers, 2021 to 2025). "The PSG3 gene had the highest expression level in both male and female tumor samples whereas PSG2, PSG7, and PSG11 had relatively lower expression levels." (PMID 40257008, 2025).
PSG11 also shares sentences with these, for which no sentence is quoted: high blood pressure (1 paper); Miscarriage (1).